ZEB1 (zinc finger E-box binding homeobox 1)
Diseases named in the same sentence as ZEB1 in open-access papers (continued):
Sharing a sentence is not in itself a finding about the gene and the disease.
breast carcinoma (continued). "On the other hand, luminal cells generally express low ZEB1 levels, and in most cases display lower expression of PKCα compared to basal-like breast cancer cells (with the exception of MDA-MB-453 cells." (PMID 31828042, 2019). "Strikingly, we observed that PKCα downregulation impaired the metastatic capacity of breast cancer cells, as we also observed for ZEB1 knockdown." (PMID 31828042, 2019). "The repressive effects of FGFR1 siRNAs on ZEB1 levels were also observed in the basal-like breast cancer, Hs-578T, and MDA-MB231 cells, which expressed FGFR1(IIIc) isoform." (PMID 31682640, 2019). "While miR-101 expression was shown to correlate with ZEB1 signaling in breast cancer cells, little is known about the role of miR-101/ZEB1 signaling in regulating the EMT process of CC." (PMID 31092700, 2019). "We found that basal-like breast cancer cell lines express high ZEB1 levels (particularly MDA-MB-231 and BT-549 cells)." (PMID 31828042, 2019). "The role for tumour stroma-derived ZEB1 in mammary tumour growth, progression and metastasis remains unexplored." (PMID 31324807, 2019). "In striking contrast, ZEB1 deletion in stromal fibroblasts strongly impairs mammary tumour progression from initiation to metastasis." (PMID 31324807, 2019). "Of note, we observe significantly upregulated ZEB1 levels in mammary tumours with abundant stroma, a characteristic indicative of poor patient prognosis." (PMID 31324807, 2019). "Conditional deletion of ZEB1 protein in the stroma of PyMT-Fib-cKO mammary tumours was confirmed by immunohistochemistry." (PMID 31324807, 2019). "Here, through the study of specimens from a large cohort of human breast cancer subjects, we showed that patients with tumors that expressed high levels of ZEB1 responded poorly to chemotherapy." (PMID 29352223, 2018). "In summary, this work provides a useful resource for the exploration of novel functions of ZEB1 in the context of breast cancer." (PMID 29744893, 2018). "Third, ZEB1 promotes DDR in breast cancer cells in response to chemotherapy and confers chemoresistance by reducing genotoxic drug-induced DSBs in an ATM-dependent manner." (PMID 29352223, 2018). "This gives a new insight into the role of ZEB2 and also perhaps of ZEB1 in breast cancer metastasis." (PMID 29963231, 2018). "Collectively, our findings suggest that ZEB1 is a crucial determinant of chemotherapeutic resistance in breast cancer." (PMID 29352223, 2018). "Taken together, we have found an important mechanism that ZEB1 regulates the sensitivity of breast cancer cells to genotoxic drug treatment in an ATM-dependent manner." (PMID 29352223, 2018). "On one hand, they negatively regulate the E-cadherin transcriptional repressors ZEB1/2 preventing EMT and on the other, they have been associated with global shifts in gene expression which promote metastatic colonization in breast cancer mouse models." (PMID 29996899, 2018). "At the molecular level, ectopic expression of ZEB1 impaired the responsiveness of breast cancer cells to genotoxic drug treatment, such as epirubicin (EPI)." (PMID 29352223, 2018).
breast carcinoma (continued). "Because depletion of ZEB1 chemosensitizes breast cancer cells in vitro and in vivo, we suggest that ZEB1-targeting agents have the potential to be used as tumor chemosensitizers." (PMID 29352223, 2018). "Fukagawa and collaborators showed in a panel of breast cancer cell lines that CDH1 has different levels of methylation that correlate with ZEB1 and ZEB2 expression levels." (PMID 30445998, 2018). "MiR-200c counteracts trastuzumab resistance by suppressing TGF-β signaling and targeting ZEB1 in breast cancer." (PMID 29950928, 2018). "This prohibited us from performing comparative ZEB1 ChIP–Seq analysis across several breast cancer models, aiming at understanding conservation and heterogeneity of ZEB1 binding in breast cancer populations." (PMID 29744893, 2018). "Our data suggest that patients are less likely to benefit from genotoxic drug-based neoadjuvant chemotherapy if they have breast cancers with high ZEB1 expression, compared with tumors with low ZEB1 expression." (PMID 29352223, 2018). "Along with the decrease in E-cadherin, co-cultured breast cancer cells had an increase ZEB1 a key markers of EMT-phenotype." (PMID 29891854, 2018). "Recently it is reported that metformin treatment transcriptionally downregulates the expression of EMT-related gene ZEB1 in breast cancer cells." (PMID 29467947, 2018). "The results demonstrated that the expression of ZEB1 was positively correlated with those of Bcl-xL and cyclin D1, highlighting that increased expression of ZEB1 contributes to the cellular mechanisms that mediate breast cancer chemoresistance." (PMID 29352223, 2018). "To assess the possible role of ZEB1 in chemoresistance, we performed immunohistochemical staining for ZEB1 in 233 cases of human breast cancer treated with anthracyclines-based neoadjuvant chemotherapy." (PMID 29352223, 2018). "In contrast, the luminal epithelial breast cancer cell line T47D exhibited essentially undetectable ZEB1 protein levels, as expected based on the mRNA profile." (PMID 29744893, 2018). "Using a nude mouse xenograft model, we further confirmed that ectopic expression of ZEB1 decreased breast cancer responsiveness to EPI treatment in vivo." (PMID 29352223, 2018). "In this study, we provide evidence that the EMT regulator ZEB1 plays an important role in breast cancer chemoresistance by increasing HR-mediated DNA damage repair." (PMID 29352223, 2018). "The third lesson derived from the ZEB1 knockout analysis was the relative inability to revert the mesenchymal Hs578T breast cancer cells to epithelial cells." (PMID 29744893, 2018). "Although zinc finger E-box binding homeobox 1 (ZEB1) has been identified as a key factor in the regulation of breast cancer differentiation and metastasis, its potential role in modulating tumor chemoresistance has not been fully understood." (PMID 29352223, 2018). "Our results showed that ZEB1 binds to the miR-190 promoter and transcriptionally suppresses miR-190 expression, suggesting that ZEB1 promotes breast cancer metastasis and EMT phenotype through inhibition of miR-190 expression." (PMID 29510731, 2018). "Despite this clear picture derived from mRNA analyses, our effort to generate an equivalent result based on ZEB1 protein analysis across a panel of 15 human breast cancer cells, succeeded with only a small subset of these cell models (data not shown)." (PMID 29744893, 2018). "ZEB1 in the progression of breast cancer controlled the production of IL-6 and IL-8, along with the initiation of EMT." (PMID 30306207, 2018). "Here we show by overexpression of FOXP3 and/ or miR-155 that in aggressive breast cancer lines ZEB2 is regulated independently of ZEB1, both transcriptionally, by FOXP3 and post-transcriptionally by miR-155." (PMID 29963231, 2018). "We further performed immunohistochemical staining for ZEB1, Bcl-xL and cyclin D1 in an independent cohort of 139 cases of primary breast carcinoma." (PMID 29352223, 2018).
breast carcinoma (continued). "Control of oncogenes, including ZEB1 and ZEB2, is a major checkpoint for preventing cancer, and loss of this control contributes to many cancers, including breast cancer." (PMID 29963231, 2018). "Basal‐A and luminal epithelial breast cancer cells expressed low or undetectable levels of ZEB1 (and ZEB2)." (PMID 29744893, 2018). "It is widely accepted that ZEB-1 is involved in cancer invasion in different tumors, including breast cancer, renal cell carcinoma and esophageal squamous cancer." (PMID 29866111, 2018). "Up-regulation of Erk signaling increases Zeb1 transcription expression level and β-catenin translocation to nucleus to regulate breast cancer stem cells." (PMID 30158579, 2018). "Accordingly, by examining 156 primary breast cancer specimens, we confirmed that ZEB1 is overexpressed in cancer tissues, and its expression is inversely correlated with that of NGN3." (PMID 28903350, 2017). "Using a nude mouse xenograft model, we further confirmed that the downregulation of ZEB1 expression restores the responsiveness of breast cancer cells to antiestrogen therapy in vivo." (PMID 28383555, 2017). "The binding of ZEB1 to the ER-α promoter in breast cancer cells provided further evidence that the downregulation of ER-α by ZEB1 is a possible functional mechanism for eliminating ER-α in ZEB1-positive breast cancer cells." (PMID 28383555, 2017). "By studying specimens from a large cohort of subjects with breast cancer, we found a strong inverse correlation between ZEB1 and ER-α protein expression." (PMID 28383555, 2017). "Third, the downregulation of ZEB1 considerably increases the responsiveness of breast cancer cells to antiestrogen therapy in vitro and in vivo, and this effect was ER-α dependent." (PMID 28383555, 2017). "To assess the influence of ZEB1 expression on breast cancer initiation in vivo, we performed extreme limiting dilution analysis to detect ZEB1-induced CSC frequencies." (PMID 28903350, 2017). "In this study, we demonstrate a mechanism for ZEB1/ER-α-mediated antiestrogen resistance in breast cancer by which ER-α promoter methylation and histone deacetylation are established." (PMID 28383555, 2017). "Knockdown of ZEB1 in human breast cancer cells reduces β-tubulin isotype classes I, III, and IVB mRNA, whereas upregulation of ZEB1 was associated with increases in these isotype classes." (PMID 28677634, 2017). "In breast cancer tissue sections we found robust co-expression of ZEB1 and HAS2 in tumor cell areas, whereas tumor cells missing ZEB1 were also negative for HAS2." (PMID 28086235, 2017). "It has been shown that miR-103/107 induces EMT in breast cancer by downregulating miR-200, which targets the E-cadherin negative regulators ZEB1 and ZEB2." (PMID 28974015, 2017). "Considering that estrogen induces ZEB1 expression while regulating breast cancer development and progression, we therefore suggest a potential role for ZEB1 at an intersection between intrinsic and acquired resistance to antiestrogen therapy." (PMID 28383555, 2017). "For example, BCL6 induced EMT by promoting the ZEB1-mediated transcription repression of E-cadherin in breast cancer cells." (PMID 28583190, 2017). "Two recent studies demonstrate that OVOL2 inhibits EMT in the mouse mammary gland and human breast cancer cells through the transcriptional inhibition of ZEB1." (PMID 28455959, 2017). "Here we provide an alternative mechanism for ZEB1/Ngn3–mediated stemness acquisition in breast cancer cells that involves methylation and deacetylation of the Ngn3 promoter." (PMID 28903350, 2017). "Over the past few years, Zeb1 has increasingly been considered as an important contributor to the process of malignancies including endometrial cancer, breast cancer, lung adenocarcinomas as well as cervical cancer." (PMID 29207526, 2017).
breast carcinoma (continued). "In a study using doxorubicin-resistant MCF-7 breast cancer cells, loss of miRNA-200c was associated with decreased E-cadherin and PTEN expression, and increased ZEB1 and p-Akt expression, which ultimately caused chemoresistance." (PMID 29029445, 2017). "Here, we report that ectopic expression of zinc finger E-box binding homeobox 1 protein (ZEB1) results in the acquisition of CSC properties by breast cancer cells, leading to tumor initiation and progression in vitro and in vivo." (PMID 28903350, 2017). "To examine the effect of ZEB1‐regulated secretory proteins on the accumulation and maturation of MDSCs in vivo, we established murine breast cancer 4T1 cells that overexpressed mouse ZEB1 (4T1‐ZEB1)." (PMID 28618162, 2017). "Several cell signaling pathways, such as transform growth factor β (TGF-β), Wnt, integrin and Notch, have been shown to induce EMT by activating transcription factors Snail, Slug, Twist and Zeb1/2 in breast cancer." (PMID 29383144, 2017). "OVOL2 has been implicated in the regulation of EMT process in the mouse mammary gland and human breast cancer cells through the transcriptional inhibition of ZEB1." (PMID 28455959, 2017). "In the present study, an essential role for ZEB1 in tumor initiation and maintenance in vitro and in vivo was confirmed by deleting ZEB1 in pre-existing breast cancer cells (MDA-MB-231 and SUM-159)." (PMID 28903350, 2017). "Prat and coworkers in their study involving breast carcinoma patients have positively correlated low expression of E-cadherin with high level of expression of mesenchymal markers including Snail, Twist and Zeb1." (PMID 28186986, 2017). "After co-culture with CXCR2+ MDSCs system, breast cancer cells exhibited mesenchymal-like morphology, the expression of ZEB1, Snail and N-cadherin was up-regulated, and ZO1 was down-regulated." (PMID 29383101, 2017). "No peaks were found at the ESRP2 and CDH1 gene loci in MCF7 cells, which likely reflected the low expression of ZEB1 in luminal‐type breast cancer cells." (PMID 28618162, 2017). "To better understand the correlation between ZEB1 and ER-α, we divided 248 cases of human breast carcinoma into two groups based on ZEB1 expression scores." (PMID 28383555, 2017). "The secretory proteins regulated by ZEB1 enhanced breast cancer cell proliferation and tumor growth." (PMID 28618162, 2017). "Immunohistological analysis of human breast cancer specimens revealed a strong inverse relationship between ZEB1 and NGN3 protein expression." (PMID 28903350, 2017). "In breast cancer cells, MiR-9 targeted ZEB1 gene, inhibited endothelial differentiation pathway and HCC proliferation by suppressing TAZ gene expression." (PMID 28868238, 2017). "SNAIL knock-down in human MDA-MB-231 breast cancer cells was associated with the induction of MET, loss of ZEB1 and reactivation of E-CADHERIN, indicating that cells have adopted an E phenotype." (PMID 28768501, 2017). "It has been known that TNF-α promotes EMT by up-regulating transcription factors such as Twist1/2, Snai1/2 and Zeb1/2 in renal cell carcinoma, breast cancer cell and colon cancer cell." (PMID 28550311, 2017). "In this study, we demonstrated an alternative mechanism for ZEB1/ER-α–mediated antiestrogen resistance in breast cancer that supplements the promoter methylation and deacetylation of ER-α." (PMID 28383555, 2017). "Vice versa, overexpression of ZEB1 in the epithelial MCF7 breast cancer cell line resulted in downregulation of E-cad and a slight activation of HAS2." (PMID 28086235, 2017). "Here, we employed chromatin immunoprecipitation sequencing (ChIP‐seq) and RNA sequencing (RNA‐seq) to investigate the transcriptional program that is regulated by ZEB1 in several basal‐type breast cancer cell lines." (PMID 28618162, 2017). "RB1 knockdown induces EMT events by lessening expression of E-cadherin as well as EMT-related factors Slug and Zeb-1 in breast cancer cells." (PMID 28716024, 2017).
breast carcinoma (continued). "Our results were consistent with the findings regarding miR-205 in NPC, however, another study in breast cancer showed that miR-205 promoted radiosensitivity by targeting ZEB1 and Ubc13." (PMID 27974696, 2017). "Based on the regulatory mechanisms of genes zeb1 and cdh1 in the growth and development of breast cancer cells, we propose a kinetic model at the level of single cell." (PMID 28852133, 2017). "ZEB1 expression in breast cancer cells also affected the growth of fibroblasts in cell culture, and the accumulation of myeloid‐derived suppressor cells in tumors in vivo." (PMID 28618162, 2017). "Second, ZEB1 expression is higher than and is inversely correlated with the amount of ER-α protein in breast cancer patients." (PMID 28383555, 2017). "To further strengthen the pathological correlation between ZEB1/Ngn3 expression and breast cancer cell stemness, we performed immunohistochemical staining for ZEB1, NGN3 and ALDH1 in 156 primary breast carcinoma patient specimens." (PMID 28903350, 2017). "In cell lines and primary breast cancer tissue, ZEB1 reduces the expression of Both RAB25 and ESRP1, which have tumor suppressor functions." (PMID 26646320, 2016). "After exposure of breast cancer cells to NC, they showed inhibited metastasis ability of breast cells by inhibiting the expression of transcription factors (Snail, Slug and Zeb1) and EMT markers." (PMID 27313840, 2016). "In the present study, we investigated the effect of miR-340 on the breast cancer progression, and the relationship between miR-340 and ZEB1." (PMID 27036021, 2016). "Nuclear expression of ZEB1 was significantly correlated with nuclear expression of YAP in breast cancer." (PMID 26876920, 2016). "Our previous study showed that ectopic expression of ZEB1 induces breast cancer metastasis through activation of the MAPK signaling, including increased phosphorylation of p38." (PMID 26882471, 2016). "For the MCF10A to MDA-MB-231 comparison, MSigDB gene expression datasets defining breast cancer cell subtypes were used to select well-established EMT associated genes (VIM, CDH1, ZEB1) as central nodes to define an IPA gene association network." (PMID 26783963, 2016). "What's more, miR-200c restored trastuzumab sensitivity in trastuzumab-resistant cells and suppressed invasion of breast cancer cells by silencing of ZEB1, ZNF217 or blockade of TGF-β signaling." (PMID 27036021, 2016). "Immunohistochemistry confirmed that ZEB1 is strongly expressed in TN breast cancer, as compared to other cancers." (PMID 26646320, 2016). "Collectively, we found that ZEB1-expressing breast cancer cells increase VEGFA production and thus stimulate tumor growth and angiogenesis via a paracrine mechanism." (PMID 26882471, 2016). "ZEB1 protein levels were rated IHC 1+ in 15 breast cancer samples, IHC 2+ in 16 samples, and IHC 3+ in 5 samples." (PMID 26646320, 2016). "In breast cancer tissues, expression of ZEB1 was positively correlated with those of VEGFA and CD31." (PMID 26882471, 2016). "In a study employing breast cancer cell lines expressing one of the two isoforms of PR, either PR-A or PR-B, ZEB1 was found to be up-regulated specifically by PR-B." (PMID 26797644, 2016). "ERK 2 was reported to induce EMT through transcriptional activation of Zeb1/2 in breast cancer cells." (PMID 27197891, 2016). "Taken together, these observations suggest that ZEB1-expressing breast cancer cells have elevated VEGFA production and thus stimulate tumor angiogenesis via a paracrine mechanism." (PMID 26882471, 2016). "In breast cancer cells, activation of CD44s upregulates the transcriptional repressor ZEB1, which binds the promoter of the splicing factor ESRP1, resulting in self-sustaining ZEB1 and CD44 expression." (PMID 27009862, 2016). "We have confirmed that tumors with high levels of ZEB1 exhibit a dramatically increased blood vessel density in breast cancer specimens." (PMID 26882471, 2016).